PTH (parathyroid hormone)
Diseases named in the same sentence as PTH in open-access papers (continued):
Sharing a sentence is not in itself a finding about the gene and the disease.
nephrolithiasis (continued). "Initially, serum calcium and parathyroid hormone (PTH) levels were markedly elevated with kidney stones and fractures prominent." (PMID 32148764, 2020). "Until 2019, she experienced recurrent nephrolithiasis, with a serum Ca level of 2.56 mmol/L, iCa level of 1.31 mmol/L, and PTH level of 2189.4 pg/mL." (PMID 33101196, 2020). "The second concern is PHPT leading to deterioration in kidney function via nephrolithiasis/nephrocalcinosis or direct effects of serum calcium or PTH on renal function." (PMID 30761868, 2019). "We aimed to determine the associations of rs7652589 with nephrolithiasis-related ESRD, Ca, P, ALP, PTH, response to treatment with cinacalcet, prevalence of coronary artery disease, and all-cause/cardiovascular mortality in HD patients (n = 1162)." (PMID 27739473, 2016). "The A allele of CASR rs7652589 was also a significant determinant of nephrolithiasis-related ESRD among other possible determinants such as gender, age, serum concentrations of Ca and PTH, and the G allele of CCL2 rs1024611." (PMID 27739473, 2016). "This case is in full accordance with a primary role of IGF1-mediated, PTH-independent increase in calcitriol synthesis resulting in hypercalciuric kidney stones." (PMID 24616756, 2013). "Increases in PTH levels with age are major factors responsible for age-related increase in bone resorption, and contribute to kidney stone formation as well." (PMID 19825157, 2009). "The intake of calcium supplements should be reduced to a minimum: due to the lack of PTH-driven reabsorption of calcium in the distal convoluted and connecting tubule, there is an impeding risk of nephrolithiasis and nephrocalcinosis." (PMID 39636417, 2024). "In comparison to the research by Daudon M, our study has identified new drugs associated with nephrolithiasis among the top 30, such as immunomodulators (AUBAGIO), proton pump inhibitors (PREVACID, NEXIUM), and parathyroid hormone-related drugs (TERIPARATIDE, NATPARA, FORTEO)." (PMID 39764463, 2024). "Our results suggest that low PTH levels may contribute to the pathogenesis of kidney stones as well as the bone phenotype in patients with AN by reducing bone formation and adding to the disturbance in mineralization." (PMID 32219087, 2020). "He had renal cysts and kidney stones after age 50, with normal serum calcium and PTH." (PMID 32311048, 2020). "Gender, age, serum concentrations of Ca and PTH, the G allele of CCL2 -2518 A > G (rs1024611), and the A allele of CASR rs7652589 were entered into the multivariate stepwise linear regression model as possible determinants of nephrolithiasis-related ESRD." (PMID 27739473, 2016). "The aim of the study was to determine the associations of the CASR rs7652589 SNP with nephrolithiasis-related ESRD, Ca, P, alkaline phosphatase (ALP), PTH, response to treatment with cinacalcet, prevalence of CAD, including MI, as well as all-cause and cardiovascular mortality in HD patients." (PMID 27739473, 2016). "We screened the kidney stones associated variants for their association to serum level of biochemical traits and detected association of variants at ALPL with ALP, SLC34A1 with PTH, and creatinine, phosphate and CLDN14 with PTH, magnesium and potassium." (PMID 26272126, 2015). "Compared with group A, parathyroid hormone (PTH) was significantly lower and clinical manifestations were milder, and the percentage of asymptomatic patients was higher in group B. Bone pain (46.8%), nephrolithiasis (37.3%), and fatigue (36.2%) were the most common symptoms in symptomatic patients." (PMID 41509026, 2026). "Due to the strong, well-documented association between nephrolithiasis and PHPT, guidelines from the American Urological Association and the European Association of Urology recommend measuring serum calcium concentration, followed by serum parathyroid hormone levels, if there is suspicion of PHPT." (PMID 38143641, 2023).
nephrolithiasis (continued). "Therefore, the development of kidney stones despite elevated PTH levels in patients with CKD may reflect a problem with PTH or calcium sensing receptor function in the renal tubule." (PMID 30760766, 2019). "A baseline blood sample to measure PTH, serum adjusted calcium and eGFR, fasting urine for measurement of urinary calcium/creatinine ratio and renal ultrasound to establish pre-treatment status regarding possible nephrocalcinosis/nephrolithiasis should be performed." (PMID 31196103, 2019). "Signs and symptoms, like with PHPT, are related to the level of PTH and calcium elevation and include soft tissue or vascular calcifications, skeletal pain, decreased BMD, fractures, muscle weakness, nephrolithiasis, peptic ulcer disease, pancreatitis, and changes in mental status." (PMID 40177730, 2025). "For patients with recurrent MEN1-related PHPT who do not meet surgical indications or refuse to be operated, cinacalcet can only maintain normal ranges of serum calcium and PTH, not reduce the risks of complications like fractures and kidney stones." (PMID 37795364, 2023). "Of note, using US only, another study from our group was unable to show any differences in serum PTH or urinary calcium between NPHPT patients with or without kidney stones." (PMID 35437440, 2022). "During the 2-year follow-up period, the patient did not experience relapse of nephrolithiasis, and the levels of serum PTH, calcium, and phosphorus were maintained at the respective normal values." (PMID 36434624, 2022). "During the 2-year follow-up period, nephrolithiasis did not relapse, and serum PTH, calcium, and phosphorus levels were normal." (PMID 36434624, 2022). "On the other hand, index case ME0292’s sister presented with high intact PTH levels and nephrolithiasis without other remarkable symptoms." (PMID 33536578, 2021). "At these loci, we also observed genome-wide significant associations with serum calcium, phosphate, PTH and ALP that do not in all cases correlate with the corresponding kidney stone association signal." (PMID 26272126, 2015). "Case 1: a 62-year-old gentleman with a background of nephrolithiasis, constipation, thalassaemia minor and non-insulin-dependent diabetes was admitted with an asymptomatic, left-sided large neck mass, raised serum calcium (2,92 mmol/L), elevated PTH (391.7 pg/ml) and polyuria." (PMID 31142320, 2019).
Insulin resistance (86 papers, 2009 to 2026). Increased resistance towards insulin, that is, diminished effectiveness of insulin in reducing blood glucose levels. "Further exploring the relationship between VDD with glucose intolerance, insulin resistance and the role of parathyroid hormone as an underlying factor in these associations is important to better understand the impact of vitamin D on development of GDM." (PMID 36703113, 2023). "This proves that among vitamin D-deficient obese women, those with a higher PTH level are at increased risk of developing insulin resistance." (PMID 34950730, 2021). "Defective insulin signaling associated with insulin resistance and response to PTH or PTHrP are involved in the activation of a proinflammatory response and the release of cytokines." (PMID 32751307, 2020). "There is evidence that vitamin D deficiency is associated with increased PTH levels coexisting with insulin resistance." (PMID 32932777, 2020). "PTH plays a role in increasing the cardiovascular risk possibly via its effects on blood pressure, insulin resistance, hyperglycaemia and low HDL-CHO levels." (PMID 24618074, 2014). "The relationship between PTH and insulin resistance needs to be investigated further, as does the mechanism responsible for causing serum PTH levels to rise with increased adiposity." (PMID 23596520, 2013). "Recent studies also suggest that increased levels of PTH are independently associated with insulin resistance in individuals with abdominal obesity suggesting a direct link between PTH and MetS." (PMID 23228198, 2012). "Firstly, excess PTH may disturb the ability of the beta cells to improve insulin secretion appropriately, causing insulin resistance through a calcium-dependent mechanism." (PMID 37051200, 2023). "How the association between PTH and insulin resistance relates to a reduced bone turnover in patients with type 2 diabetes is not well understood, but a possible mechanism may be elicited by osteocytic dysfunction with excess production of sclerostin." (PMID 35422766, 2022). "Indirectly, low vitamin D status could stimulate parathyroid hormone release, which has been shown to be associated with insulin resistance." (PMID 35906229, 2022). "We report a positive association between change in HOMA-IR and PTH supporting a hypothesis of insulin resistance as a potential key factor in the expanding field of bone fragility in T2D subjects." (PMID 35422766, 2022). "Furthermore, PTH is associated with insulin resistance, and one study showed that PTH decreased insulin-stimulated glucose absorption in rat adipocytes." (PMID 35209709, 2022). "Vitamin D deficiency is also related to increased levels of PTH associated with insulin resistance." (PMID 30959886, 2019). "In addition, an elevated level of intact parathyroid hormone was significantly associated with lower risk of death in patients with insulin resistance (HR, 0.19; 95% CI, 0.05–0.66; p = 0.009)." (PMID 31181824, 2019). "The combination of high PTH and insulin resistance could potentiate the risk of cardiovascular complications." (PMID 24026893, 2013). "GLUC, glucose; TGL, triglycerides; CHOL, cholesterol; HDL, high-density lipoprotein; LDL, low-density lipoprotein; HOMA-IR, homeostatic model assessment for insulin resistance; Corr, calcium-corrected; PTH, Parathyroid hormone." (PMID 37965235, 2023). "OB people also had lower IGF1 (P < 0.05), and 25OHD (P < 0.001) and higher PTH (P < 0.05), insulin, glucose, homeostatic model assessment for insulin resistance (HOMA-IR) (all P < 0.001) than NW people." (PMID 36173650, 2022). "There were significant differences in the homeostasis model assessment of insulin resistance, folic acid, vitamin D, iron, ferritin, and parathyroid hormone levels (P < .05)." (PMID 36197162, 2022). "Vitamin D deficiency increase serum parathyroid hormone levels (PTH) and the PTH plays an important role in NAFLD through increasing insulin resistance (IR)." (PMID 34803681, 2021).
Insulin resistance (continued). "Vitamin D also affects insulin resistance by regulating the production of the parathyroid hormone, which in turn increases intracellular Ca++ concentration while leading to decreased GLUT4 activity and the reduced uptake of glucose." (PMID 33923190, 2021). "PTH also has been reported to down-regulate insulin intracellular signaling, resulting in an increase in peripheral insulin resistance, and is also inversely correlated with insulin sensitivity." (PMID 33207657, 2020). "PTH hypersecretion can be found in insulin resistance, together with metabolic acidosis, excess glucocorticoid secretion, chronic low-grade inflammation, and excess angiotensin II." (PMID 32751307, 2020). "PTH was positively associated with BMI, WC, SBP, DBP, TG, and insulin resistance and negatively associated with HDL-C17." (PMID 32081877, 2020). "Oral vitamin D supplementation reduced the hypersecretion of parathyroid hormone and insulin resistance in obese Chinese males." (PMID 29692809, 2018). "Increased stages of fibrosis were primarily associated with higher levels of HOMA2-insulin resistance (IR), procollagen type I propeptide (P1NP), lower osteocalcin, albumin-corrected calcium, parathyroid hormone, vitamin D, male sex, and higher age." (PMID 26989059, 2016). "Patients with CKD commonly exhibit increased insulin resistance and i-PTH but decreased vitamin D levels." (PMID 26083479, 2015). "It is possible that temporary insulin resistance at the dinner time induced rapid elevation in glucose and insulin levels, and suppressed PTH secretion in Late-D." (PMID 26450680, 2015). "On other hand, it has also been demonstrated that PTH stimulates the adipose tissue differentiation and increases insulin resistance in these cells in correlation to the adipose tissue mass." (PMID 25886602, 2015). "A few studies have described a positive relationship between PTH and insulin resistance similar to our observation in univariate analyses." (PMID 23596520, 2013). "Concentration of 25(OH) D, calcium, phosphorous, parathyroid hormone (PTH), fasting blood glucose, HbA1c, serum insulin, homeostasis model assessment of insulin resistance (HOMA-IR) was determined in the fasting samples." (PMID 23497722, 2012). "Prior data have shown the involvement of PTH in insulin resistance development." (PMID 40283231, 2025). "In support of the numerous studies on the importance of inflammation in the development of insulin resistance and alterations in glucose metabolism, at the three time points considered, we found significantly higher levels of PTH and PCR in patients belonging to the AMG+ group." (PMID 38794758, 2024). "Also female gender, BMI, bilirubin, serum calcium, serum phosphorus PTH, fasting insulin, and insulin resistance were statistically significant predictors of OP among the NAFLD group." (PMID 36928441, 2023). "Thus, PTH promotes insulin resistance by reducing glucose absorption in the liver, muscle, and adipose tissue." (PMID 35209709, 2022). "We did find an association between increase in PTH and increase in insulin resistance in all subjects independent of the dietary intervention." (PMID 35422766, 2022). "Black people have lower levels of vitamin D and higher levels of PTH compared to White people, so the negative association between vitamin D and insulin resistance should be stronger." (PMID 36313112, 2022). "For this, researchers analyzed vitamin D and calcium supplementation together, as when combined, they can exert activity on oxidative stress through cell cycle regulation, activation of antioxidant enzymes, and PTH suppression, generally improving insulin resistance and the inflammatory processes." (PMID 35052633, 2022). "Parathyroid hormone (PTH) can mediate insulin resistance by inhibiting insulin signaling and reducing glucose uptake, while vitamin D could exert an insulin-improving effect by reducing PTH levels." (PMID 36313112, 2022).
Insulin resistance (continued). "It implies that improvement of the vitamin D status can suppress the PTH that may ameliorate insulin resistance in obese subjects." (PMID 34950730, 2021). "Interestingly, these genes are associated with metabolic pathways such as endocrine disorders, glucagon signaling, parathyroid hormone, and insulin resistance." (PMID 34707105, 2021). "It has been hypothesized that serum levels of calcium, phosphorus and PTH can be effective on insulin resistance." (PMID 34505755, 2021). "Prevalence of insulin resistance, though negatively correlated with vitamin D, could be better explained by BMI and PTH levels." (PMID 34950730, 2021). "Therefore, both growing intracellular Ca2+ concentration and the decreasing number of GLUT-1 and GLUT-4 on the cell membranes evoked by PTH promotes insulin resistance observed as reduced glucose uptake." (PMID 32932777, 2020). "Thus, PTH promotes insulin resistance via reduction of glucose uptake in adipose tissue, liver, and muscle." (PMID 30959886, 2019). "Absence of PTH measurement was another important limitation, since it has been implicated in pathogenesis of insulin resistance and metabolic syndrome." (PMID 22966228, 2012). "In addition, the relationship between PTH and MS was robust after adjustment for possible confounders including age, gender, BMI, serum calcium, phosphate, magnesium, vitamin D levels, insulin resistance and type 2 diabetes." (PMID 19187564, 2009). "According to previous experiments, the effect of vit D on blood lipids may be due to the inhibition of parathyroid hormone (PTH) secretion, as elevated PTH has been shown to have a positive association with higher WC, suppressed lipolysis, and insulin resistance." (PMID 37727395, 2023). "We did find an association between measures of insulin resistance and levels of circulating PTH levels, which supports the hypothesis that insulin resistance may be key to understand the low bone turnover and increased bone fragility observed in subjects with T2D." (PMID 35422766, 2022). "We measured parathyroid hormone (PTH), 25-hydroxyvitamin D, bone mineral density (BMD), hemoglobin A1c (HbA1c), serum albumin (ALB), and Homeostatic Model Assessment for Insulin Resistance (HOMA-IR)." (PMID 40313432, 2025). "BMI, body mass index; GLUC, glucose; TGL, triglycerides; CHOL, cholesterol; HDL, high-density lipoprotein; LDL, low-density lipoprotein; HOMA-IR, homeostatic model assessment for insulin resistance; Corr, calcium-corrected; PTH, Parathyroid hormone." (PMID 37965235, 2023). "A homeostatic model of insulin resistance (HOMA-IR) was assessed, in addition to serum concentrations of fasting blood glucose (FBG), HbA1C, (25(OH) D), and PTH." (PMID 32659891, 2020). "Plasma fasting glucose, insulin, homeostasis model assessment insulin resistance (HOMA-IR), 25-hydroxyvitamin D, parathyroid hormone and androgen levels were measured before and after treatment." (PMID 25246913, 2012). "PTH also induced an increase of insulin receptor substrate-1 (IRS-1) phosphorylation on serine 307, which has been reported to down-regulate insulin intracellular signaling, resulting in an increase in peripheral insulin resistance." (PMID 33207657, 2020). "The positive correlation between serum PTH and blood pressure has been confirmed, but not between PTH and insulin resistance, blood glucose or blood lipids." (PMID 21306649, 2011). "However, repeated daily PTH administration failed to sustain adipose browning or improve insulin resistance and hyperglycemia; instead, it exacerbated weight gain, primarily due to increased food intake." (PMID 42231020, 2026). "We confirm a positive correlation between serum PTH and blood pressure, but we could not verify any correlations between PTH and insulin resistance, blood glucose or blood lipids." (PMID 19187564, 2009).